PSEN1 (presenilin 1)
Diseases named in the same sentence as PSEN1 in open-access papers (continued):
Sharing a sentence is not in itself a finding about the gene and the disease.
dementia (continued). "Here, we performed a systematic screening of known dementia-causing genes (APP, PSEN1, PSEN2, or GRN genes) in 821 PD cases and 423 controls from North America in addition to 553 PD patients and 550 healthy controls from Spain." (PMID 29692703, 2018). "In addition to the clinical overlap between dementia and parkinsonism in carriers of PSEN1 mutations, there is extensive Lewy body pathology in early-onset AD carriers of the PSEN1 p.S170F and PSEN1 p.A431V mutations suggesting an interaction between PSEN1 dysfunction and α-synuclein aggregation." (PMID 29692703, 2018). "Autosomal dominant AD (ADAD) is a rare form of AD, caused by mutations in genes encoding presenilin-1 (PSEN1), presenilin-2 (PSEN2), or amyloid precursor protein (APP) and leading to young onset dementia." (PMID 25922840, 2015). "Mutations in the APP, PSEN1, PSEN2, and MAPT genes give rise to well-characterized differential neuropathological and clinical phenotypes of dementia." (PMID 22482072, 2012). "Pathogenic mutations in APP, PSEN1, PSEN2, MAPT and GRN have previously been linked to familial early onset forms of dementia." (PMID 22312439, 2012). "The prevailing pathogenic model for dementias caused by mutations in APP and genes that regulate APP processing (PSEN1, PSEN2 and BRI2/ITM2b) posits that amyloid peptides trigger dementia." (PMID 23217200, 2012). "Mutated forms of both amyloid precursor protein (APP) and presenilin 1 (PS1) lead to an increased rate of amyloid deposition and therefore an earlier onset of the dementia associated with AD." (PMID 15689237, 2005). "The world second case of complete protection from familial AD was also discovered in the Columbian familial AD cohort and was identified in a male patient carrying the PSEN1 E280A mutation who was first diagnosed with MCI at the age of 67 years and progressed to mild dementia by the age of 72 years." (PMID 40275327, 2025). "There were no genome-wide or suggestive associations with genetic variants in known causal Mendelian dementia genes (APP, PSEN1, PSEN2, and GRN), suggesting that common variants in these genes do not significantly contribute to sporadic EOAD, or that we do not have enough power." (PMID 38883718, 2024). "First, several major YOD risk factors, such as APOE ε4 alleles; APP, PSEN1, and PSEN2 genes; family history of dementia; history of traumatic brain injury; hearing loss; and education level could not be obtained." (PMID 38926887, 2024). "Patients suffering from familial AD (fAD) develop cognitive impairment and dementia between 50 and 65 years and bear mutations in one of the three genes involved in the β-amyloidogenic pathway: APP, presenilin 1 (PSEN1), and presenilin 2 (PSEN2); increased APP dosage is also causative of AD and CAA." (PMID 39475348, 2024). "The sample size was small because of the rare occurrence of APP duplication and PSEN1 mutations and the additional specific inclusion criteria (e.g. known genetic mutation status and absence of dementia)." (PMID 39713236, 2024). "PSEN1 E280A carriers develop dementia by midlife, but there is variability in disease trajectory." (PMID 37612284, 2023). "However, the clearest indicator for disease heterogeneity in FAD, as an effect of individual modifying factors, is that age of dementia onset ranges from 37 to 77 years old among PSEN1 E280A carriers." (PMID 37264439, 2023). "Individuals belonging to the “Paisa pedigree,” affected by AD, carry a deleterious variant in the Presenilin 1 (PSEN1) gene and most will develop dementia before their 50th birthday (we have coined the term the Paisa pedigree, making reference to the clan cluster with this homogeneous form of AD)." (PMID 31664702, 2020). "We performed whole genome sequencing and proved that PSEN1 but not other susceptible genes for dementia contributing to the genetic cause of the frontal variant of AD." (PMID 32477171, 2020).
dementia (continued). "Notably, the reported Japanese patient with PSEN1 P284L who developed spastic paresis preceded dementia at her thirties." (PMID 30090657, 2018). "Notably, enhanced hippocampal activation has been observed in cognitively normal carriers of apolipoprotein E4 (ApoE4) or presenilin 1 (PS1) gene mutations, and these individuals also have an increased risk of developing dementia." (PMID 30135948, 2018). "PSEN1 mutants promote neurodegeneration and dementia without any increase in Aβ, suggesting the causal roles of PSEN1 mutants in AD via an Aβ-independent manner." (PMID 27926491, 2017). "Indeed a familial form of AD, associated with deletion of exon 9 of Presenilin 1 (PSEN1) has a clinical presentation highly similar to FBD, with subjects developing spastic paraparesis prior to onset of dementia." (PMID 26405694, 2015). "A novel variant in GRN, p.C247Y and a known variant in PSEN1, p.R35Q were found in demented individuals with a non-AD CSF profile suggesting another type of dementia." (PMID 23990795, 2013). "In this study, we observed a known and confirmed pathogenic mutation (PSEN1 p.A426P, rs63751223) in one individual (57 years old) without a clear family history of dementia, out of 258 individuals (CDR>0), which constitutes 0.3% of AD cases." (PMID 23990795, 2013). "PSEN1 mutations can also determine early-onset “pure” parkinsonism, without dementia phenotype." (PMID 37648940, 2023). "Moreover, ulcerative colitis was recently linked to dementia, but the potential role of the presenilin 1(PS1)/BACE-1/beta-amyloid (Aβ) axis has not been evaluated." (PMID 36386153, 2022). "The aim of the present study was to determine whether MSL prevented early progression of dementia in AD-related amyloid precursor protein (APP)/presenilin 1 (PS1) double transgenic mice, and to explore the potential mechanisms of action involved in neuronal protection." (PMID 29636677, 2018). "Mutations in these genes confer specific phenotypic profiles to patients with dementia: amyloidogenic pathology associated with APP, PSEN1, and PSEN2 mutations and tauopathy associated with MATP mutations, representing the two major pathogenic hypotheses for AD." (PMID 22482072, 2012). "PSEN1 E280A carriers from this cohort present mild cognitive impairment (MCI) at a median age of 44 and dementia at 49 years of age." (PMID 40275327, 2025). "Significant dockings (with confidence scores greater than 0.7) were identified in these experiments involving OMdP in bEVs with several dementia-related proteins, including AD-neuropathological markers, such as APP, PrP, TAU, and PSEN1." (PMID 41237903, 2025). "Searching for other dementia cases resulted in the identification of APP p.A713T in one DLB case and PSEN1 p.A79V in a possible AD case according to ADSP diagnosis criteria." (PMID 39606324, 2024). "Additionally, a predicted LOF variant in PSEN1, p.Gly206Ala (rs63750082), exhibited an association with dementias (phecode = 290.1, OR = 17.3, P = 9.79 × 10–10), while a neutral variant in PSEN1, p.Glu318Gly (rs17125721), did not demonstrate such an association (P = 0.86)." (PMID 38037155, 2023). "Since PSEN1 E280A LOFAD patients show less pTau, together with specific kinases and kinome profiles, a link between dementia onset and pTau pathology can be suggested." (PMID 33319314, 2021). "Given the very rare frequency of APP, PSEN1, and PSEN2 pathogenic mutations detected in the screened patients (two individuals with EOAD), our hypothesis should encourage genetic screening in larger cohorts of both EOAD and LOAD, as well as dementia cases using the gene panel." (PMID 30917570, 2019). "Some molecular mechanisms explained the pathological development of early-onset dementia progression, including mutations in the amyloid precursor protein (APP) gene, as well as presenilin 1 or 2 (PS1 or PS2) genes, which are closely related to the early onset of dementia." (PMID 39350383, 2024).
dementia (continued). "None of these patients had a family history of stroke or dementia, and none had any pathogenic mutation in the APP, PSEN1 and PSEN2 genes to explain early Aβ pathology." (PMID 29450646, 2018). "This analysis revealed that variants in the PSEN1 (HR = 6.2; 4.6–8.2) and GRN (HR = 9.9; 5.0–19.6) genes significantly increased the risk of dementia (data not shown)." (PMID 25333068, 2014). "To investigate this intriguing hypothesis, we analyzed rare coding variability in 6 Mendelian dementia genes (APP, PSEN1, PSEN2, GRN, MAPT, and PRNP), in 141 LOAD patients and 179 elderly controls, neuropathologically proven, from the UK." (PMID 25104557, 2014). "GWASs have shown that common noncoding variability in Mendelian dementia genes (APP, PSEN1, PSEN2, MAPT, GRN, and PRNP) does not influence susceptibility to AD." (PMID 25104557, 2014). "(x) APOE may also interact with PSEN1, ACE, A2M, and other genes to regulate the effect of drugs on cognition and behavioral changes in dementia." (PMID 22482072, 2012). "Thus, we screened 6 Mendelian dementia genes (APP, PSEN1, PSEN2, MAPT, GRN, and PRNP) aiming to establish whether rare coding variability in these genes is responsible for an appreciable portion of the LOAD risk." (PMID 25104557, 2014). "In a clinical setting, we recommend to examine an extended panel of dementia genes in familial EOAD, when APP, PSEN1, and PSEN2 are tested negative, as was suggested before." (PMID 35650585, 2022).
Cognitive impairment (83 papers, 2008 to 2026). Abnormal cognition is characterized by deficits in thinking, reasoning, or remembering. "5xFAD mice express 5 familial AD mutations resulting in overexpression of APP and PSEN1 and exhibit early onset amyloid pathology and cognitive deficits." (PMID 39919123, 2025). "We identified associations with cognitive impairment specifically in the CNV mutations of the PSEN1 (exons 1, 9, 12), GRN (exons 1, 6, 12), and MAPT (exons 2, 8) genes." (PMID 40725212, 2025). "PSEN1-L226F mutation is closely related to the occurrence of mental disorders and subsequent cognitive impairment, as well as the occurrence of depressive symptoms." (PMID 39135796, 2024). "Carriers of the PSEN1 E280A mutation develop mild cognitive impairment at 43–45 and dementia at 49–50 years of age (95% confidence intervals); the identified female patient did not develop mild cognitive impairment until her seventies." (PMID 38571814, 2024). "APP and PSEN1 mutations in mouse neurons have been shown to induce behavioral and cognitive deficits in different mouse models." (PMID 38473822, 2024). "In a study conducted on aged mice, it was found that methylglyoxal, which causes oxidative damage to proteins, increases oxidative stress and causes AD‐like cognitive impairment, as well as ROS formation and increased PSEN1 gene expression." (PMID 37772794, 2023). "Individuals carrying the PSEN1 p.E280A mutation typically develop mild cognitive impairment at a median age of 44 years (95% confidence interval [CI]: 43‒45 years) and dementia at a median age of 49 years (95% CI: 49‒50 years)." (PMID 35641666, 2023). "We characterized a male heterozygous for the RELN-COLBOS variant who was resilient to the cognitive impairment associated with the PSEN1-E280A mutation." (PMID 37188781, 2023). "Recently, it was reported that a de novo PSEN1 mutation is responsible for an early-onset parkinsonism with cognitive impairment." (PMID 29692703, 2018). "Those mice harbor transgenes for human amyloid precursor protein (APP) bearing the Swedish mutation and a deletion mutant form of presenilin 1, and present increased Aβ production and cognitive deficits." (PMID 25617315, 2015). "The 3xTgAD mice express mutant presenilin-1, amyloid precursor protein and tau, and exhibit AD-like amyloid and tau pathology in the hippocampus and cortex, and associated cognitive impairment." (PMID 18648646, 2008). "Patients with the reported P284S and P284L mutations and other PSEN1 gene mutations at nearby sites were associated with the pyramidal system, spastic paraparesis, prominent MRI white matter hyperintense lesions, and cerebral microhemorrhage, except for memory loss and cognitive deficits." (PMID 35850649, 2022). "A recent single case publication showing that a patient with a presenilin 1 mutation was resistant to cognitive impairment, likely due to a homozygous mutation in APOE, supports the hypothesis that APOE might play an important role in this tau pathology acceleration." (PMID 31866851, 2019). "A detailed statistical analysis of the different exons of the PSEN1, MAPT, and GRN genes in relation to the significantly associated cognitive impairment domains was conducted based on MoCA data." (PMID 40725212, 2025). "Several associations between CNV mutations in genes (APP, GRN, MAPT, PSEN1, PSEN2) and various domains of cognitive impairment were identified." (PMID 40725212, 2025). "The 5xFAD mouse, which highly expresses mutant human APP and PSEN1, is frequently used for investigating AD pathology in vivo, including amyloid plaque formation and cognitive impairment." (PMID 38472795, 2024). "These mice co-expressed amyloid precursor protein and presenilin-1, showing plaque aggregation and significant cognitive impairment at 8 months." (PMID 37686830, 2023).
Cognitive impairment (continued). "Acetylcholinesterase binds directly to presenilin-1 (PS-1), an essential enzyme in the Aβ synthesis pathway, and increases its expression, raising the amount of Aβ and accelerating cognitive impairment." (PMID 37035098, 2023). "Double transgenic mice overexpressing the amyloid precursor protein (app) and presenilin-1 (psen-1) genes (tastpm), which are a preclinical model of familial AD, displayed an increased latency to heat in parallel with cognitive deficits at 6 months." (PMID 35955710, 2022). "APP/PS1 double transgenic mice overexpress human amyloid precursor protein (APPsw) and mutant forms of presenilin 1 (m146L) genes, which are characterized by early amyloid deposition and early cognitive impairment and glymphatic dysfunction." (PMID 36032783, 2022). "Our laboratory has shown that oral CBD treatment prevents cognitive impairment in a male genetic mouse model of AD, the amyloid precursor protein 1 x presenilin 1 hemizygous (APPxPS1) mouse." (PMID 36238565, 2022). "The APP/PSEN1-Tg model of AD recapitulates the early-depressive, early-anxiety and other early-cognitive impairment manifestations before developing AD, as a prodromal stage of the neurodegenerative disease." (PMID 33795014, 2021). "Since 5xFAD mice include five familial AD (FAD) mutations consisting of amyloid protein precursor (APP) and presenilin-1 (PSEN1), they showed Aβ plaques and cognitive impairment in the early stage." (PMID 34439569, 2021). "In fact, only 3 out of 12 PSEN1 E280A carriers were older than 40 years of age and presented with cognitive impairment." (PMID 33319314, 2021). "The transgenic mice expressing human APP/PSEN1-Tg carrying familial AD mutations used in these studies (B6C3-Tg) have an onset of plaque pathology at around 6 months, which is followed by cognitive impairments with both increasing by 12–18 months of age." (PMID 33795014, 2021). "FTP levels correlated with cognitive impairment, showed faster aggregation kinetics and its binding was observed only in PSEN1 E280A carriers that already show substantial Aβ deposition levels in cortical regions." (PMID 33319314, 2021). "A previous study with carriers of the PSEN1 E280A mutation identified a pre-MCI stage, characterized by memory complaints and coexisting objective cognitive impairment." (PMID 25922840, 2015). "Our findings showed that PSEN1 CNV mutations in exons 1, 9, and 12 were associated with specific cognitive deficits and helped distinguish patients based on the presence and type of cognitive impairment." (PMID 40725212, 2025). "However, it is important to mention that the results from patients with PSEN1, SQSTM1, VCP, and ANXA11 mutations highlight distinct patterns of cognitive impairment, reflecting both shared and gene-specific features of neurodegeneration." (PMID 40649976, 2025). "MGO induces cognitive impairment and presenilin-1 expression in aged mice." (PMID 39574138, 2024). "Accordingly, the present study sheds new light on the emerging role of HIIT combined with CBD supplementation in improving AD progression via modulating the expression of APOE, presenilin-1, and glutamate proteins, reducing Aꞵ plaque, apoptosis, and decreasing cognitive impairment." (PMID 39539449, 2024). "We first estimated the age-related trajectory of cognitive impairment as a function of APOE e2 genotype separately in PSEN1 E280A mutation carriers and non-carriers." (PMID 37612284, 2023). "Surprisingly, a woman with homozygous APOEChc variant and carrying the PSEN1 p.E280A mutation did not exhibit mild cognitive impairment until her 70 s even though abundant accumulation of amyloid-β (Aβ) was seen in the brain." (PMID 35641666, 2023). "We then estimated the age-related trajectory of cognitive impairment as a function of APOE e4 genotype separately in PSEN1 E280A mutation carriers and non-carriers." (PMID 37612284, 2023).